PTPRG (protein tyrosine phosphatase receptor type G)
Diseases named in the same sentence as PTPRG in open-access papers (continued):
Sharing a sentence is not in itself a finding about the gene and the disease.
leukemia (2 papers, 2017 to 2021). A malignant (clonal) hematologic disorder, involving hematopoietic stem cells and characterized by the presence of primitive or atypical myeloid or lymphoid cells in the bone marrow and the blood. "Investigations carried out in the various leukemia and lymphoma subgroups report a significant involvement of PTPRG underlined by multiple data obtained on the epigenetic mechanisms affecting this gene." (PMID 35071225, 2021). "The evaluation of larger series of leukemia samples (myeloproliferative diseases, CML, and ALL) for PTPRG expression by flow cytometry, in addition to in situ techniques, as well as the detailed definition of its signaling pathway, may reveal additional details regarding CML biology." (PMID 28637510, 2017).
lung carcinoma (2 papers, 2019 to 2021). "Intriguingly, PTPRG expression is also downregulated in lung cancer." (PMID 31012177, 2019).
arrhythmogenic right ventricular cardiomyopathy (1 paper, 2014). "The RNA expression in PTPRG has been reported to be upregulated for arrhythmogenic right ventricular cardiomyopathy in humans." (PMID 25519402, 2014).
behavioral disorders (1 paper, 2022). "PTPRG has important roles in human diseases; for example, neuropsychiatric and behavioral disorders and various types of cancer such as colon, ovary, lung, breast, central nervous system, and inflammatory disorders." (PMID 35053232, 2022).
cerebral infarction (1 paper, 2020). An ischemic condition of the brain, producing a persistent focal neurological deficit in the area of distribution of the cerebral arteries. "Loss-of-function variants in PTPRG, encoding RPTPγ, are associated with increased risk of cerebral infarction, heart attack, and reduced cardiac ejection fraction." (PMID 32955439, 2020).
chordoma (1 paper, 2011). Chordomas are rare malignant tumors arising from embryonic remnants of the notochord in axial skeleton. "This region contains multiple genes, including RBM5, FHIT and PTPRG, but their involvement in chordoma pathogenesis has yet to be determined." (PMID 22613809, 2011).
Fuchs' corneal dystrophy (1 paper, 2014). "A meta-analysis of TCF4 and PTPRG gene variants in Fuchs' corneal dystrophy (FCD)." (PMID 25299301, 2014).
gestational diabetes (1 paper, 2022). Carbohydrate intolerance first diagnosed during pregnancy. "Although many aspects are to be clarified, an early study demonstrates a consistent increase in PTPRG in the GDM (gestational diabetes mellitus) group compared with the control, identifying it as a possible disease biomarker." (PMID 35053232, 2022).
heart attack (1 paper, 2020). "The risk of self-reported heart attacks was greatly elevated (~4 fold) amongst individuals carrying loss-of-function PTPRG variants of moderate and high impact." (PMID 32955439, 2020).
ischemia (1 paper, 2020). A hypoperfusion of the BLOOD through an organ or tissue caused by a PATHOLOGIC CONSTRICTION or obstruction of its BLOOD VESSELS, or an absence of BLOOD CIRCULATION. "We conclude that PTPRG is an ischemia susceptibility locus; and RPTPγ-dependent sensing of HCO3– adjusts endothelium-mediated vasorelaxation, microvascular perfusion, and blood pressure during acid-base disturbances and altered tissue metabolism." (PMID 32955439, 2020). "Evidence connecting acid-base sensors to human disease has so far been scarce; but in the current study, we identify PTPRG as an ischemia susceptibility locus, which is supported by a recent meta-analysis of genome-wide association studies linking PTPRG to ischemic stroke in African Americans." (PMID 32955439, 2020).
ischemic heart disease (1 paper, 2020). "We observed a significantly lower left ventricular ejection fraction in carriers of high-impact loss-of-function PTPRG variants compared to non-carriers consistent with the greater risk of ischemic heart disease." (PMID 32955439, 2020).
malignant glioma (1 paper, 2017). A grade III or grade IV glioma arising from the central nervous system. "Taken all together; however, it is possible to postulate that selective inhibitors of the R5 RPTP subfamily members, PTPRZ and PTPRG, may be applicable to a differentiation-inducing therapy for malignant gliomas." (PMID 28717188, 2017).
Merkel cell carcinoma (1 paper, 2024). "MCPyV causes the skin cancer Merkel cell carcinoma by integrating it’s genome into the human receptor tyrosine phosphatase type G gene (PTPRG) resulting in the production of MCPyV ST and LT antigen-PTPRG fusion transcripts." (PMID 39516641, 2024).
myeloma (1 paper, 2025). "Because IFN-γ robustly induces PD-L1 in myeloma plasma cells, reduced PTPRG would be expected to prolong/augment STAT1 signaling and enhance PD-L1 induction, whereas higher PTPRG should blunt this response." (PMID 41050668, 2025). "However, the involvement of PTPRG in plasma cell myeloma has not been well explored, and it remains unclear whether PTPRG dysfunction might promote therapy resistance in MM and involved signaling pathways." (PMID 41050668, 2025).
osteosarcoma (1 paper, 2024). A usually aggressive malignant bone-forming mesenchymal neoplasm, predominantly affecting adolescents and young adults. "Two human cell lines—ACC-LC-171 non–small-cell lung carcinoma and the U-2 OS osteosarcoma—each transcribe the normal 6.2-kb and 9.6-kb human PTPRG mRNAs, but each also generates two additional mRNAs." (PMID 38952869, 2024). "These authors detected the expression of extra 4.5-kb and 6.8-kb mRNAs in ACC-LC-171 human non–small-cell lung carcinoma cells and of 7.6-kb and 10.8-kb mRNAs in U-2 OS osteosarcoma cells, detected by using Northern blot analysis using a 2.8-kb EcoRI fragment of a partial PTPRG cDNA clone." (PMID 38952869, 2024).
retinal disease (1 paper, 2017). "According the paper, among these DEGs, PTPRG, CSPG5 and NAV3 are at loci associated with retinal disease; MFAP3L, CSPG5 and PAK1IP1 locate in the regions carrying SNP's significantly associated with AMD." (PMID 28924976, 2017).
rhabdomyosarcoma (1 paper, 2021). A rare aggressive malignant mesenchymal neoplasm arising from skeletal muscle. "Moreover, PTPRG could also modulate the activity of FGFR4 in rhabdomyosarcoma, indeed using siRNA against PTPRG in FGF-treated RH30 cell line increases phosphorylation of the receptor FGFR4 and downstream molecule such as PLCG1 (Phospholipase C-gamma 1) compared to the scramble control." (PMID 35071225, 2021).
schizoaffective disorder (1 paper, 2014). "Gene PTPRG has previously been found to be associated with schizoaffective disorder." (PMID 27605030, 2014).
Stroke (1 paper, 2020). Sudden impairment of blood flow to a part of the brain due to occlusion or rupture of an artery to the brain. "The risk of self-reported stroke also showed a strong tendency toward elevation—with borderline statistical significance—amongst the carriers of moderate- and high-impact loss-of-function PTPRG variants." (PMID 32955439, 2020).
tumor (44 papers, 2008 to 2026). "PTPRG, therefore, represented an appealing tumor suppressor gene candidate and research over the years yielded many different ways by which the function of RPTPγ, its encoded protein, can be impaired." (PMID 36755664, 2022). "In order to obtain functional evidence to support the suppressive role of PTPRG-associated Akt inhibition in vivo, the effects of Akt inhibition on the in vivo tumor growth were investigated using a nude mouse tumorigenicity assay." (PMID 25970784, 2015). "In this current study, we identified the potential PTPRG-associated signaling pathways and protein-interacting partners that impact its tumor and metastasis suppressive roles in NPC." (PMID 25970784, 2015). "Of note, PTPRG is a reported tumor suppressor with roles in neuropsychiatric and inflammatory disorders." (PMID 41333442, 2025). "The apparent contrast between PTPRG’s canonical tumor-suppressive role elsewhere and its adverse prognostic association in MM likely reflects substrate and network context-dependence." (PMID 41050668, 2025). "PROX1, a member of the homeobox transcription factor family with both oncogenic and tumor suppressive characteristics, exhibited increased gene expression after PTPRG silencing." (PMID 41323734, 2025). "Protein tyrosine phosphatase receptor gamma (PTPRG) has emerged as a candidate tumor suppressor in various malignancies by antagonizing proliferative and survival signaling, but its functional and prognostic relevance in MM has not been established." (PMID 41050668, 2025). "In particular, Protein Tyrosine Phosphatase Receptor Type G (PTPRG) stands out as a candidate tumor suppressor and signaling modulator in hematologic malignancies." (PMID 41050668, 2025). "Further work is needed to understand the expression patterns of RASSF6 and PTPRG, which are generally considered to be tumor suppressors and genes like BIRC3 and CDKN1A that are known to be involved in a number of different cancers." (PMID 37910143, 2023). "The prediction was confirmed at the mRNA and protein level, further validating the approach and identifying a new molecular mechanism of tumor suppression governed by PTPRG in a CML context." (PMID 36077295, 2022). "On the basis of this evidence and other evidence, PTPRG has been recognized as a tumor suppressor gene, and numerous findings report an impaired tumorigenic after introduction or re-expression of PTPRG." (PMID 35053232, 2022). "The gene encoding for this phosphatase is located in a chromosomal region (3p21-p14.2) frequently deleted in renal cell and lung carcinoma, where PTPRG acts as a tumor suppressor in many cancers." (PMID 36077295, 2022). "Protein tyrosine phosphatase receptor gamma (PTPRG) is a well-known tumor suppressor in various neoplasms." (PMID 36568252, 2022). "Clinical samples showed significant downregulation of the following genes: CPT2, ACAA2, HPGD and ALDH3A2, while the expression of ENO2, TDO2, CPOX, ACADL and PTPRG was significantly upregulated in the tumor tissue (p < 0.01)." (PMID 36230866, 2022). "Protein tyrosine phosphatase receptor gamma (PTPRG) is known to interact with and regulate several tyrosine kinases, exerting a tumor suppressor role in several type of cancers." (PMID 35053232, 2022). "Protein tyrosine phosphatase receptor gamma (PTPRG) is a member of the receptor-like family protein tyrosine phosphatases and acts as a tumor suppressor gene in different neoplasms." (PMID 33893334, 2021). "In summary, in this study, we have shown that the expression of PTPRG, a tumor suppressor gene, is suppressed in CML patients and this can be restored following treatment with TKIs to levels observed in healthy controls." (PMID 33893334, 2021). "Additional genes with potential tumor suppressor function that have been shown to be involved in MCPyV integration include PTPRG, GRWD1, and XRCC4." (PMID 32878339, 2020).
tumor (continued). "The gene encoding for this phosphatase is located in a chromosomal region (3p21-p14), frequently deleted in renal cell and lung carcinoma, where PTPRG acts as a tumor suppressor." (PMID 32225105, 2020). "DNMT1 and DNMT3b cooperate for tumor suppressor silencing, and we observed a higher expression of these two proteins in K562 cells, as compared to PTPRG-expressing LAMA-84." (PMID 32225105, 2020). "PTPRG is a tumor suppressor gene capable of interfering with BCR-ABL1 signaling by decreasing BCR-ABL1-dependent tyrosine phosphorylation in CML cells." (PMID 28637510, 2017). "Consistent with previous studies showing that PTPRG is a candidate tumor suppressor, MCF-7 and MDA-231 cells transfected with PTPRG siRNA showed significantly increased proliferation." (PMID 27602768, 2016). "Our earlier NPC study also confirmed that re-expression of PTPRG suppressed in vivo tumor growth and induced cell cycle G0/G1 arrest by down-regulation of cyclin D1 protein levels and, thus, reduced phosphorylation of pRB." (PMID 25970784, 2015). "The results also validated the role of PTPRG in tumor suppression through inhibition of Akt signaling." (PMID 25970784, 2015). "Functional studies suggested that re-expression of PTPRG induced significant tumor suppressive effects in different cancers." (PMID 25970784, 2015). "These experiments provide direct evidence to support the functional effects of Akt inactivation in cancer and support our finding showing that PTPRG re-expression inhibits cell proliferation and in vivo tumor growth via Akt inhibition." (PMID 25970784, 2015). "A tumor-suppressive PTPRG-expressing clone and vector-alone (VA), which were previously established in the HONE1 NPC cell line engineered with a tetracycline-regulated inducible (tet-off) system, were used for this antibody array study." (PMID 25970784, 2015). "PTPRG demonstrates ubiquitous expression across mammalian tissues, while manifesting significant downregulation in various malignancies, a characteristic indicative of its tumor suppressor function." (PMID 41323734, 2025). "The various evidence supported that PTPRG was a tumor suppressor gene in many cancers." (PMID 36405010, 2022). "Interestingly, except for a tumor suppressor within the cancer cells, PTPRG was also reported as a key node of the immunophenotype regulation hub, indicating its potential to improve immunotherapeutic effects." (PMID 36405010, 2022). "Arimura reported PTPRG was least expressed in immune cells, B cells, in particular, suggesting it might be engaged in suppressing tumor growth and metastasis through regulation downstream signals and actions of immune cells." (PMID 35433461, 2022). "In addition, PTPRG seems to directly dephosphorylate β-catenin, providing further details on its tumor-suppressive effects in CML." (PMID 34065882, 2021). "Hence, in the present study, we demonstrated that cMras inhibited tumour growth and metastasis, working as a sponge of miRNA‐567 to directly restrain its activity, and subsequently upregulated its target PTPRG to exert its tumour suppressor function in LUAD." (PMID 31012177, 2019). "Furthermore, we found that miR‐567 or siRNA against PTPRG weaken the suppressive effect of cMras overexpressing tumours." (PMID 31012177, 2019). "PTPRG is emerging as a key tumor suppressor gene in many types of neoplasia." (PMID 28637510, 2017). "In this current study, the tumor suppressive role of PTPRG was investigated." (PMID 25970784, 2015). "Results suggested that PTPRG was able to inhibit in vitro tumor invasion." (PMID 25970784, 2015). "β-catenin has recently been found to be the target of another phosphatase, PTP receptor type γ (PTPRG), which was originally identified as a candidate tumor suppressor gene in renal cell and lung carcinoma, localized at 3p21-p14, a genomic region which is commonly deleted in these neoplasms." (PMID 34065882, 2021).
tumor (continued). "MCPyV integration within cellular genes could also act as a mechanism of tumor suppressor gene inactivation in a subset of tumors, as potentially disruptive integration into genes with tumor suppressor roles (PTPRG, XRCC4) has been described in individual cases." (PMID 32878339, 2020). "The convergence of tumor suppression (FHIT, FAM107A), metabolic reprogramming (PDHB), and immune/signaling (PTPRG, FAM3D) genes within a single genomic region suggests a potential resistance-associated haplotype block." (PMID 42302616, 2026). "A number of Protein Tyrosine Phosphatases (PTPs) have been described in human cancers as tumour suppressor genes and among the most studied include PTPRM;, PTPN13; and PTPRG;." (PMID 38475971, 2024). "Altogether, these results highlighted the pivotal role of PTPRG and CHL1 in tumor growth and progression of ccRCC." (PMID 35433461, 2022). "Upon 5‐aza treatment, a down‐regulated expression of two tumour suppressors, THBS4 and PTPRG were restored, as well as a potential epigenetic diagnostic marker CMTM28 and miR200c involved in activation of Notch pathways in CTCL." (PMID 32794659, 2020). "Among them, only EMP1, PTPRG and DDX17 were downregulated in LUAD tissues by the analysis of TCGA database, suggesting their tumour suppression role." (PMID 31012177, 2019). "Clinically, up-regulation of EGFR can be detected in NPC patient biopsies, as PTPRG can induce dephosphorylation of EGFR and, thus, the downstream PI3K/Akt signaling pathway; this further supports the critical tumor suppressive role of PTPRG in NPC." (PMID 25970784, 2015). "In order to further confirm the role of Akt inhibition in tumor suppression in NPC cells, Akt inhibition in the two NPC tumorigenic PTPRG-down-regulated cell lines, HONE1 and HK1, was further investigated." (PMID 25970784, 2015). "This hypothesis was supported by our snRNA-seq analysis, in which we clearly observed that genes related to neuronal migration and axon guidance (CNTN1, PTPRG, NTRK2, FAT3, etc.)were more upregulated in neuron cell clusters than in tumor cell clusters." (PMID 38609519, 2024). "As a result, we observed that neuron-related genes (CNTN1, FAT3, PTPRG, NTRK2, etc.)annotated to categories such as nervous system development, neuron differentiation, generation of neurons, and neurogenesis were downregulated in tumor cluster cells (Online Resource)." (PMID 38609519, 2024). "In conclusion, our study divided ccRCC into distinct immune clusters and thereby identified two DEGs, namely, PTPRG and CHL1, which were validated to play a crucial role in inhibiting tumor growth and might be responsible for the formation of distinct immune clusters in ccRCC." (PMID 35433461, 2022). "Finally, these genes were overlapped with the upregulated DEGs from the two GSE9782 datasets, resulting in 7 tumor stemness-related genes, including NONO, CBX3, SLC25A3, PTPRG, NPM1, HINT1, HNRNPA1." (PMID 41050668, 2025).